DMD (dystrophin)
Diseases named in the same sentence as DMD in open-access papers (continued):
Sharing a sentence is not in itself a finding about the gene and the disease.
Duchenne muscular dystrophy (continued). "Duchenne’s muscular dystrophy is a condition in which a lack of dystrophin results in progressive loss of muscle strength and ultimately to death from respiratory or cardiac failure." (PMID 32918390, 2020). "Duchenne muscular dystrophy (DMD) is an X-linked recessive disorder caused by the lack of dystrophin encoded by the DMD gene." (PMID 32650783, 2020). "Duchenne muscular dystrophy (DMD) is a severe form of muscular dystrophy caused by lack of dystrophin, leading to membrane instability and increased probability of damage during contraction." (PMID 32023816, 2020). "The dystrophin or DMD (Duchenne muscular dystrophy) gene consists of 79 canonical exons (CEs)." (PMID 33050418, 2020). "Duchenne muscular dystrophy (DMD) is the most common lethal childhood neuromuscular disease, and it is caused by loss of function mutations in the X-linked DMD gene that codes for dystrophin protein." (PMID 33057138, 2020). "Duchenne muscular dystrophy (DMD) is a severe neuromuscular disease that affects 1 in 3500 boys and is characterized by progressive degeneration of striated muscle cells resulting from mutations in or loss of the cytoskeletal protein dystrophin." (PMID 31286350, 2020). "Duchenne muscular dystrophy (DMD) is a severe hereditary disease caused by a lack of dystrophin, a protein essential for myocyte integrity." (PMID 33228255, 2020). "Duchenne muscular dystrophy (DMD) is a severe X-linked muscle-wasting condition caused by an absence of the functional dystrophin protein that primarily affects the fast-glycolytic fibres." (PMID 32033037, 2020). "Duchenne muscular dystrophy (DMD) is an X-linked disorder caused by the lack of dystrophin with progressive degeneration of skeletal muscles." (PMID 32760246, 2020). "Cav-3 overexpressing transgenic mice revealed severely affected symptoms with an increase in the number of sarcolemmal caveolae, which is one of the Duchenne muscular dystrophy traits in humans, and the downregulation of dystrophin and β-dystroglycan protein expression." (PMID 32825241, 2020). "The reduction in levels of expression of dystrophin isoforms in Drosophila using RNAi led to muscle degeneration in larval and adult flies, thus potentially providing a useful model to help us understand Duchenne muscular dystrophy pathogenesis in humans." (PMID 33080928, 2020). "Additionally, recent reports described the use of gold nanoparticles for the delivery of clustered regularly interspaced short palindromic repeats CRISPR/Cas9 for the editing of the CXCR4 gene or the dystrophin gene, associated with Duchenne muscular dystrophy (DMD) disease." (PMID 32560390, 2020). "A significant percentage of Duchenne muscular dystrophy (DMD) cases are caused by premature termination codon (PTC) mutations in the dystrophin gene, leading to the production of a truncated, non-functional dystrophin polypeptide." (PMID 32858918, 2020). "However, PTC124 has been sufficient to restore function to the dystrophin gene in a mouse model of Duchenne muscular dystrophy." (PMID 33396210, 2020). "Duchenne muscular dystrophy (DMD) is a rare, severe and progressive neuromuscular disease caused by a mutation in the dystrophin gene, lead to a deficiency in the production of dystrophin." (PMID 32785240, 2020). "Duchenne muscular dystrophy (DMD) is a lethal X‐linked recessive pathology in which lack of functional dystrophin leads to progressive muscle degeneration culminating in loss of locomotion and premature death." (PMID 30912260, 2019). "DUSP1/MKP-1 has also been implicated in muscle regeneration as DUSP1−/− mice are impaired in their ability to recover from experimental muscle injury and, when crossed into a mouse model of Duchenne's muscular dystrophy (the mdx dystrophin null), they display exacerbated muscular dystrophinopathy." (PMID 30401534, 2019).
Duchenne muscular dystrophy (continued). "Finally, DMD-iPSCs (clone ID: CiRA00111) isolated from a Duchenne muscular dystrophy patient harboring a deletion of exon 4452 were targeted for exon 45 skipping by the CRISPR-Cas3 system." (PMID 31811138, 2019). "Duchenne Muscular Dystrophy (DMD) is an X-­linked genetic disease characterized by the lack of the Dystrophin protein in the muscle tissue of affected individuals." (PMID 29862132, 2018). "Duchenne Muscular Dystrophy (DMD) is the most common X-linked lethal disorder in humans affecting up to 1 in 3500 live male births, with about a third of cases being due to new spontaneous mutations in the dystrophin gene." (PMID 29561896, 2018). "Recently, the CRSIPR/Cpf1-mediated dystrophin knock-out pigs, and phospholamban knock-in pigs with a 3-nt deletion in the presence of a single-stranded oligo donor, have been established as a Duchenne muscular dystrophy (DMD) and dilated cardiomyopathy (DCM) models, respectively." (PMID 30233645, 2018). "In genetic myopathies such as Duchenne muscular dystrophy (DMD), a fatal X-linked recessive muscle disease caused by genetic mutations leading to the loss of dystrophin, repeated cycles of muscle injury, and repair result in increased variation of fiber size and muscle fibers with central nuclei." (PMID 30336774, 2018). "Duchenne muscular dystrophy (DMD) and Becker muscular dystrophy (BMD) are muscular wasting disorders that affect both skeletal and cardiac muscle and result from mutations in the dystrophin gene." (PMID 30396907, 2018). "Clinical trials using strategies aimed at inducing dystrophin expression in Duchenne muscular dystrophy (DMD) are underway or at advanced planning stage, including splice switching antisense oligonucleotides (AON), drugs to induce read-through of nonsense mutations and viral mediated gene therapy." (PMID 29579078, 2018). "Duchenne muscular dystrophy (DMD) is a progressive X-linked neuromuscular disease affecting 1 in 3500 to 5000 live male births, which arises from the ablation of the cytoskeletal protein, dystrophin." (PMID 27921261, 2017). "Duchenne muscular dystrophy (DMD), Becker muscular dystrophy (BMD), and X-linked dilated cardiomyopathy (XL-DCM) consist of a unique clinical entity, the dystrophinopathies, which are due to variable mutations in the dystrophin gene." (PMID 29367543, 2017). "Duchenne muscular dystrophy (DMD) is a fatal genetic disease caused by an absence of the 427kD muscle-specific dystrophin isoform." (PMID 29045431, 2017). "In some myopathies like Duchenne muscular dystrophy (DMD) where there is a deficiency in the structural protein dystrophin, a characteristic loss of SCs has been observed to be associated with repeated cycles of degeneration–regeneration, and allografts of SCs have been tested in DMD patients." (PMID 28464938, 2017). "Duchenne muscular dystrophy (DMD) is a progressive muscle degenerative disease caused by mutations in the dystrophin gene that disrupt the reading frame and lead to loss of functional dystrophin expression." (PMID 28238287, 2017). "Duchenne muscular dystrophy (DMD) is an X-linked disorder caused by various mutations in the gene encoding for dystrophin, resulting in the absence of the functional protein in muscle fibres." (PMID 28403854, 2017). "Duchenne Muscular Dystrophy is a rare and fatal neuromuscular disease in which the absence of dystrophin from the muscle membrane induces a secondary loss of neuronal nitric oxide synthase and the muscles capacity for endogenous nitric oxide synthesis." (PMID 28545481, 2017). "Duchenne muscular dystrophy (DMD) affects approximately one of every 3,300 male births worldwide, and is caused by mutations in the gene encoding for the myocyte structural protein dystrophin." (PMID 28219442, 2017).
Duchenne muscular dystrophy (continued). "The reduction of dystrophin expression constitutes the structural basis in the hearts of patients with Becker muscular dystrophy and the absence of dystrophin is associated with Duchenne muscular dystrophy." (PMID 29267303, 2017). "Mutations in the Duchenne muscular dystrophy (DMD) gene result in decreased to absent dystrophin protein expression." (PMID 28028563, 2017). "Duchenne Muscular Dystrophy (DMD) is a severe and progressive muscle-wasting disorder caused by mutations in the DMD gene located on chromosome Xp21, which are mostly intragenic deletions (72%) resulting in loss of one or more exons and disruption of the dystrophin open reading frame." (PMID 27612288, 2016). "Duchenne muscular dystrophy (DMD) is a lethal inherited muscle wasting disease caused by mutations in the dystrophin gene that disrupt the open reading frame, preventing production of a functional dystrophin protein." (PMID 26974331, 2016). "Duchenne muscular dystrophy (DMD) is a genetic disease characterised by skeletal muscle degeneration and progressive muscle wasting, which is caused by loss-of-function mutations in the DMD gene that encodes for the protein dystrophin." (PMID 29188075, 2016). "The loss of other DGC components in the absence of dystrophin is common with other models of Duchenne muscular dystrophy (DMD) such as the mdx mouse, and in people with DMD." (PMID 26604135, 2016). "Another notable example is in the null mutation of the dystrophin gene, which reduces the lifespan of individuals with Duchenne muscular dystrophy (DMD) by ~75%; while dystrophin-deficient mice display minimal clinical symptoms and only a ~25% reduction in lifespan." (PMID 26870043, 2016). "Duchenne muscular dystrophy (DMD; OMIM #310200) is an X-linked recessive, severe and progressive muscle disease with a prevalence of 1 in 3,500 live male births, and is caused by mutations in the dystrophin gene." (PMID 27977725, 2016). "Duchenne muscular dystrophy (DMD) is an X-linked muscle-wasting condition caused by low or absent expression of the muscle protein dystrophin, leaving muscle fibres exquisitely vulnerable to exercise-induced damage (particularly eccentric exercise)." (PMID 27525173, 2016). "It has achieved greatest maturity in exon skipping of the dystrophin transcript in Duchenne muscular dystrophy (DMD), for which several clinical trials are completed or ongoing, and a large body of data exists describing tested oligonucleotides and their efficacy." (PMID 25816009, 2015). "When human mesenchymal stem cells are transplanted into a model of Duchenne muscular dystrophy, the stem cells contributed to myofibers and functional satellite cells, restore sarcolemmal expression of dystrophin, and enhance the expression of neurotrophic factors." (PMID 25945496, 2015). "Mutations in the Dystrophin gene often lead to a non-functional protein and Duchenne muscular dystrophy (DMD), characterised by severe muscle degeneration from early childhood." (PMID 26459831, 2015). "Duchenne muscular dystrophy (DMD) is an early onset childhood X-linked disease associated with the absence of dystrophin, a sarcolemma-associated cytoplasmic protein critical for maintaining sarcolemmal integrity of myofibers." (PMID 26500547, 2015). "The present study evaluated low-level laser therapy (LLLT) effects on some physiological pathways that may lead to muscle damage or regeneration capacity in dystrophin-deficient muscle cells of mdx mice, the experimental model of Duchenne muscular dystrophy (DMD)." (PMID 26083527, 2015). "Duchenne muscular dystrophy (DMD) is caused by genetic mutations that result in the absence of dystrophin protein expression." (PMID 25492562, 2015). "However, PTC124 treatment restored 20–25% of dystrophin protein levels in the mdx-mouse, a model for Duchenne muscular dystrophy, in vitro and in vivo." (PMID 25292197, 2015).
Duchenne muscular dystrophy (continued). "Furthermore, with the exception of myotonic dystrophy type 1, all of the genes also had intragenic SNPs represented (range: 2–78), and together with Duchenne muscular dystrophy, there were 320 intragenic SNPs across the dystrophin gene on the X chromosome." (PMID 24810687, 2014). "Duchenne muscular dystrophy (DMD) is a genetic disorder caused by the absence of dystrophin in both skeletal and cardiac muscles." (PMID 25181488, 2014). "Duchenne muscular dystrophy (DMD) is the most common hereditary muscular dystrophy caused by mutation in dystrophin, and there is no curative therapy." (PMID 24600399, 2014). "The discovery of dystrophin as the gene responsible for Duchenne muscular Dystrophy (DMD) has enabled researchers to identify several of the genes linked directly or indirectly to dystrophin and to correlate defects in those genes to many of the different forms of muscular dystrophies." (PMID 24795643, 2014). "Thus, for example, Duchenne muscular dystrophy leading to the weakness of EOMs implicates only the DMD gene located on Xp21.2." (PMID 25309358, 2014). "Duchenne muscular dystrophy (DMD) is an X-linked, lethal neuromuscular disorder caused by frame-disrupting mutations in the DMD gene, which ultimately result in the lack of functional dystrophin protein." (PMID 25365558, 2014). "Deletions encompassing one or more exons of the dystrophin gene are the most common cause of the severe Duchenne muscular dystrophy (DMD) resulting in an absence of dystrophin or expression of a non-functional protein." (PMID 24084719, 2013). "Duchenne muscular dystrophy (DMD) is an incurable, X-linked progressive muscle degenerative disorder that results from the absence of dystrophin protein and leads to premature death in affected individuals due to respiratory and/or cardiac failure typically by age of 30." (PMID 23984357, 2013). "Duchenne muscular dystrophy (DMD) and its less severe allelic form, Becker muscular dystrophy (BMD), are common X-linked recessive neuromuscular diseases caused by mutations in the DMD gene." (PMID 23453023, 2013). "Duchenne muscular dystrophy (DMD), the most severe form, is caused by mutations in the gene for DMD, leading to a near absence of functional dystrophin protein 2,3." (PMID 23560812, 2013). "A notable member of this group of debilitating disorders is Duchenne muscular dystrophy (DMD), which is caused by mutations in the gene that encodes dystrophin, a key component of the dystrophin-glycoprotein complex (DGC) that connects intracellular proteins with the extracellular matrix." (PMID 23798567, 2013). "In Duchenne muscular dystrophy the absence of dystrophin causes subclinical or clinical dilated cardiomyopathy." (PMID 23437355, 2013). "Duchenne muscular dystrophy (DMD) is an X-linked lethal genetic disease caused by the absence of the protein dystrophin." (PMID 23029189, 2012). "In mammals, the absence of the large structural muscle protein dystrophin underlies the muscle degenerative disorder Duchenne muscular dystrophy (DMD)." (PMID 22479198, 2012). "The severe muscle wasting disorder Duchenne muscular dystrophy (DMD) is caused by genetic defects in the DMD gene, leading to a complete absence of dystrophin protein." (PMID 23259153, 2012). "Thus, the monitoring of cellular immune responses should be a priority for any experimental therapy designed to increase the number of dystrophin-positive myofibers in patients with Duchenne's muscular dystrophy." (PMID 22348094, 2012). "In Duchenne muscular dystrophy the absence of dystrophin leads to a large reduction of the dystrophin associated proteins." (PMID 21179410, 2010). "Duchenne Muscular Dystrophy (DMD) is caused by an absence of the protein dystrophin as indicated by the absence of immunostaining for this protein in most of the muscle fibers." (PMID 19236710, 2009).
Duchenne muscular dystrophy (continued). "Duchenne muscular dystrophy (DMD) remains a major challenge in genetic medicine due to the difficulty of achieving durable, body-wide restoration of dystrophin in post-mitotic muscle tissues." (PMID 42193866, 2026). "Thirty years ago, in 1995, I proposed a fundamental treatment for Duchenne Muscular Dystrophy (DMD) using antisense oligonucleotides (ASOs) to induce exon skipping and restore dystrophin expression." (PMID 39941071, 2025). "In Duchenne Muscular Dystrophy 1 (D1) 1,372 proteins were identified, in DMD 2 (D2) 995 proteins were identified, in DMD 3 (D3) 1,278 proteins were identified and in DMD 4 (D4) 1,057 proteins were identified." (PMID 39865125, 2025). "Researchers have successfully used CRISPR to correct gene mutations responsible for cleidocranial dysplasia and Duchenne muscular dystrophy (DMD) in patient‐derived iPSCs, restoring normal bone formation and dystrophin protein expression, respectively." (PMID 40290901, 2025). "The DMD gene is located at chromosome Xp21.2 and is responsible for Duchenne muscular dystrophy (DMD), the most common muscular dystrophinopathy of childhood." (PMID 39673425, 2025). "Duchenne muscular dystrophy (DMD) and Becker muscular dystrophy (BMD) are rare, progressive, and X-linked recessive neuromuscular disorders caused by mutations in the Dystrophin gene (DMD) in the Xp21 region." (PMID 40822690, 2025). "A prominent example is Duchenne muscular dystrophy (DMD), whose protein product dystrophin is generated from a 11.2 kb segment of the DMD mRNA." (PMID 40493400, 2025). "Micro-dystrophin replacement gene therapy is currently under clinical trials in Duchenne muscular dystrophy (DMD) patients." (PMID 40562489, 2025). "Unlike the more severe, allelic form, Duchenne muscular dystrophy (DMD), in BMD, in-frame variants in the DMD gene allow the production of a partially functional dystrophin protein." (PMID 40483375, 2025). "Duchenne muscular dystrophy (DMD) is a severe degenerative neuromuscular disorder (NMD), caused by X‐linked inherited mutations that limit the production of dystrophin, which is a critical structural protein in the muscle fibers." (PMID 39434514, 2025). "Duchenne muscular dystrophy (DMD), one of the most prevalent and severe X-linked neuromuscular disorders, is characterized by progressive skeletal muscle degeneration, cardiomyopathy, and respiratory failure due to mutations in the DMD gene, which encodes the cytoskeletal protein dystrophin." (PMID 40558510, 2025). "Duchenne muscular dystrophy (DMD; OMIM #137215) is an X-linked recessive myopathy caused by mutations in the large DMD gene that encodes dystrophin." (PMID 38959711, 2024). "Duchenne muscular dystrophy (DMD) is the most common inherited X-linked form of muscular dystrophy, causing a severe and progressive neuromuscular disorder characterized by the insufficient production of dystrophin due to specific mutations in the dystrophin gene." (PMID 39201459, 2024). "For example, Golodirsen and Eteplirsen are FDA-approved ASOs used to treat Duchenne muscular dystrophy (DMD), which promote the skipping of an exon in the DMD gene that would otherwise produce an out-of-frame transcript." (PMID 39408823, 2024). "Duchenne muscular dystrophy (DMD, MIM310200), a lethal X-linked recessive disease caused by deficiency in dystrophin, a sarcoplasmic protein, was the first characterized and the most common inherited muscular dystrophy." (PMID 38413582, 2024). "Duchenne muscular dystrophy (DMD) and Becker muscular dystrophy (BMD) are dystrophinopathies, which are genetic disorders resulting from pathogenic variants in the DMD gene located on the X chromosome." (PMID 38693632, 2024). "The US Food and Drug Administration approved eteplirsen for Duchenne muscular dystrophy (DMD) in 2016 based on a controversial pivotal study that demonstrated a limited effect on the surrogate measure of dystrophin production." (PMID 38265797, 2024).